INS (insulin)
Diseases named in the same sentence as INS in open-access papers (continued):
Sharing a sentence is not in itself a finding about the gene and the disease.
prediabetes (continued). "One of the most extensively characterized initial signs of prediabetes is a reduction of the rate of glucose uptake by the insulin responsive cells after a meal." (PMID 33665204, 2020). "The increasing number of research on probiotics, prebiotics, and synbiotics for prediabetes leads us to believe that these interventions have improved glycemia and insulin sensitivity." (PMID 32221098, 2020). "The TRF protocol induced lower peak glucose and insulin responses during postprandial breakfast and lunch periods and holds promise for the improvement of daily glycemic control in those with prediabetes or T2DM." (PMID 32079327, 2020). "Contrary to these findings, in both older adults and those with prediabetes, the increase in whole-body insulin sensitivity following 12 weeks of aerobic exercise training was attenuated in those taking metformin concurrently." (PMID 33013705, 2020). "For example, AST enhances insulin signaling, improves glucose metabolism, and prevents steatohepatitis in the liver of insulin-resistant mice and individuals with prediabetes conditions." (PMID 32998286, 2020). "We observed, for the first time to our knowledge, that 10 weeks of HIIT in older adults with prediabetes improved glucose homeostasis and insulin sensitivity; and these beneficial responses were accompanied by improved neutrophil functions and bioenergetics." (PMID 32431698, 2020). "In conclusion, endothelial function was not improved following 2 weeks of CONT or INT exercise in people with prediabetes despite improved glucose tolerance and circulating insulin concentrations." (PMID 31976336, 2019). "Prediabetes is a state where higher insulin demands are compensated for by increased beta cell secretory activity, followed by an adaptive proliferation of beta cells." (PMID 31420552, 2019). "Bacterial species, depending on their virulence, appear to play a role in the relationship between periodontitis and prediabetes by promoting insulin resistance and β-cell compensatory response." (PMID 30039349, 2019). "A study of Japanese subjects with prediabetes indicated that insulin sensitivity (Matsuda index) was lower and EISI was significantly higher in obese subjects than nonobese subjects in each decile of 2-hour glucose level by OGTT." (PMID 31772943, 2019). "In fact, pioglitazone reduced hepatic TAG content, glucose and insulin levels in plasma, improving hepatic, muscle and adipose tissue insulin-sensitivity in patients with prediabetes or T2DM and biopsy-proven NASH." (PMID 31426291, 2019). "In our first 5-week crossover study, we found that eTRF reduces insulin levels, improves insulin sensitivity, lowers blood pressure, and decreases lipid peroxidation in men with prediabetes." (PMID 31151228, 2019). "Endothelial function is not improved consistently after short-term training, despite improvements in glucose and insulin responses to the OGTT in obese adults with prediabetes." (PMID 31976336, 2019). "IAPP and insulin are co-secreted from β-cells and since insulin secretion is increased in prediabetes to compensate for increased insulin demand, IAPP secretion is increased as well." (PMID 30989320, 2019). "We compared the impact of a high versus low energy intake first meal on glucose and insulin responses during prolonged sitting in individuals with prediabetes." (PMID 29882811, 2018). "Since insulin is necessary to remove TG from the bloodstream, high TGs are one of the first symptoms of IR in prediabetes." (PMID 29636788, 2018). "An abundance of studies has now confirmed that robust increases in insulin sensitivity occur following exercise in individuals with prediabetes or patients with T2DM." (PMID 30061841, 2018). "It is feasible that our overweight men with prediabetes are insulin resistant at the level of BAT and, as a consequence, display low [18F] FDG uptake in BAT." (PMID 30145664, 2018). "In prediabetes, resistance to insulin action is compensated by higher levels of insulin in the serum." (PMID 30360393, 2018).
prediabetes (continued). "To date, no study has determined the relative impact of energy intake or macronutrient composition on daily glucose and insulin levels in adults with prediabetes." (PMID 29882811, 2018). "Individuals with prediabetes displayed higher fasting plasma levels of glucose, insulin, C-peptide, triacylglycerol and hsCRP, HbA1c, HOMA-IR, BMI, and waist circumference compared with individuals with normal glucose regulation." (PMID 29379988, 2018). "Hypoadiponectinemia has been shown to precede a decrease in insulin sensitivity as well as predict progression from normoglycemia to prediabetes." (PMID 30069271, 2018). "Because FPIS disappears early in the prediabetes stage, it is reasonable to postulate that SPIS must be the most important cause of glucose control before insulin injection." (PMID 29377927, 2018). "During follow-up, 13 of these individuals started insulin treatment, 118 started taking oral glucose-lowering medication and 731 were diagnosed with prediabetes based on their fasting glucose levels." (PMID 27787621, 2017). "Within numerous clinical studies in the pathology of prediabetes, the changes of insulin secretion capacity and tissue insulin sensitivity have been delineated." (PMID 29046729, 2017). "Further work awaits investigation to elucidate the optimal nutrition program for maximizing improvements in hepatic and/or skeletal muscle insulin resistance during exercise interventions across the prediabetes phenotypes." (PMID 29387730, 2017). "This study showed higher incidence of prediabetes in metformin and insulin users (19.1% and 15.6%, resp)." (PMID 28491872, 2017). "The findings that the association was robust to the adjustment for baseline fasting glucose and insulin levels and that ADAMTS13 activity was also associated with incident prediabetes limit the possibility of reverse causation." (PMID 27787621, 2017). "The mean levels of FPG and 2hPG as well as insulin sensitivity and beta cell function were in the normal range in participants classified as having prediabetes by HbA1c." (PMID 28973497, 2017). "Since liver and skeletal muscle are the major tissues responsible for glucose homeostasis, the insulin resistance in different tissues and their interaction complicate the pathology of developing prediabetes." (PMID 29046729, 2017). "If true in individuals with prediabetes, this would have implications for augmenting insulin sensitivity using exercise and nutrition prescriptions categorized by prediabetes phenotype." (PMID 29387730, 2017). "In fact, our group described that chronic caffeine intake prevents and reverted the increase in blood pressure and insulin resistance in hypercaloric animal models of prediabetes." (PMID 29311923, 2017). "In conclusion, among individuals with prediabetes defined by the glucose criteria, substituting LPA with MVPA was associated with improvements in 2hPG and insulin sensitivity." (PMID 28973497, 2017). "It is well known that insulin hypersecretion is an early stage pathophysiology which occurs in genetic obesity and prediabetes." (PMID 28210227, 2017). "In a prediabetes status and during the first years of disease, blood insulin levels are elevated in DM type II, insulin generates low levels of reactive oxygen species which are integral to the regulation of a variety of intracellular signaling pathways." (PMID 29231877, 2017). "Further work is required to identify specific postexercise carbohydrate manipulations to increase insulin sensitivity among different prediabetes phenotypes." (PMID 29387730, 2017). "A second impaired feature of insulin secretion in prediabetes and T2D is pulsatile insulin delivery." (PMID 29118381, 2017). "We provide data demonstrating that overexpression of miR‐335 in the human EndoC‐βH1 cells reduce insulin secretion and that miR‐335 expression was negatively correlated with insulin secretion in human islets from individuals with prediabetes." (PMID 29122960, 2017).
prediabetes (continued). "Although carbohydrate composition modulates insulin sensitivity, few have studied effects of low glycemic index or whole-grain diets following exercise across prediabetes phenotypes on insulin sensitivity." (PMID 29387730, 2017). "A diurnal pattern of insulin sensitivity has been confirmed for both healthy persons and participants with prediabetes." (PMID 28604592, 2017). "Together, these data indicate that exercise intensity adjusts pancreatic insulin secretion uniquely between glucose regulatory tissues in the immediate post-exercise period to favor glycemic control in people with prediabetes." (PMID 27111219, 2016). "Fasting C-peptide concentrations, indicative of basal insulin secretion, were highest in subjects with prediabetes and T2D and lowest in those with LADA and T1D as expected." (PMID 27558530, 2016). "Lifestyle modifications alone are insufficient to bring down the prevalence of prediabetes, so there is a need for long-term, safe and cost-effective agents that can act through multiple mechanisms to improve insulin sensitivity and beta-cell function." (PMID 27894336, 2016). "Generally, impaired fasting glucose is predictive for prediabetes, and the onsets of T1D and T2D, such as high fasting glucose and low insulin, seem to be similar, which was why few pathways were screened from short-term animal experiments." (PMID 27291303, 2016). "We found that consuming a smoothie supplemented with blueberries for 6 weeks had a greater increase in insulin sensitivity in obese and insulin-resistant adults (i.e., prediabetes) when compared to their counterparts that consumed a placebo smoothie." (PMID 27916833, 2016). "When insulin secretion cannot maintain the degree of hyperinsulinemia required to overcome the resistance, prediabetes [impaired glucose tolerance (IGT), impaired fasting glucose] and subsequently T2DM develop." (PMID 26759114, 2016). "In the present work, we studied the interactions of mitochondrial DNA methylation with FG, A1c, and insulin sensitivity, the parameters that change stage-dependently during prediabetes progression." (PMID 27298712, 2016). "Both cross-sectional and longitudinal studies have demonstrated that prediabetes is the result of decreased insulin sensitivity and/or the inability of the β-cells to adequately compensate through increased insulin secretion." (PMID 27274905, 2016). "Fasting glucose, 2-hour oral glucose tolerance, estimated insulin sensitivity index, and plasma glucose area under the curve at baseline and after a 12-week resistance training program in the three prediabetes phenotypes." (PMID 26840904, 2016). "The data from clinical trials show that a significant number of patients with the decreased insulin sensitivity (prediabetes) in the brain demonstrated the early stages of AD." (PMID 28031898, 2015). "The OGTT results will be used to provide greater clinical insight into how the promotion of physical activity affects metabolic health in prediabetes, given 2-hour glucose and insulin levels better reflect peripheral insulin sensitivity." (PMID 26130075, 2015). "In patients with prediabetes, insulin sensitivity was lower in patients with a BMI ≥ 22.3 kg/m2 than in patients below this cut-off (Matsuda ISI 10.17 ± 6.02 vs. 14.74 ± 6.25, p = 0.11 after adjustment for gender and age)." (PMID 26398489, 2015). "Insulin levels (mRNA/protein) were higher in AT derived from prediabetes BB rats with destructed pancreatic β-cells and controls than pancreas derived from the same rats respectively." (PMID 25743104, 2015). "Beta cell function, insulin sensitivity and insulin resistance were calculated for normoglycaemic and prediabetes participants using the Homeostasis Model Assessment (HOMA-2) calculator." (PMID 24416185, 2014). "Mean baseline and 6 month values and the mean absolute changes in insulin sensitivity, insulin secretion and β-cell function in the subgroup of participants with prediabetes." (PMID 25299668, 2014).
prediabetes (continued). "In a post hoc analysis restricted to participants with prediabetes, a significant beneficial effect of vitamin D and calcium supplementation on insulin sensitivity (HOMA%S and Matsuda) was observed." (PMID 25299668, 2014). "In a post hoc analysis restricted to participants with prediabetes, there was a significant between group difference for the change in insulin sensitivity, as assessed by HOMA%S and Matsuda, in favor of the vitamin D and calcium supplementation group." (PMID 25299668, 2014). "Serum glucose and insulin concentrations for all participants (calculated from fasting blood samples collected on test days) fell below cut-offs for prediabetes (glucose <5.55 mmol/L) and insulin resistance (serum insulin <18 μU/mL)." (PMID 23537225, 2013). "Mean serum zinc and mean serum insulin levels were significantly different between normoglycemic and prediabetes participants." (PMID 23613929, 2013). "Second, our study demonstrated that subjects with IGM had both reduced beta-cell function and decreased insulin sensitivity, which confirms previous reports of a decline in pancreatic beta-cell function in prediabetes." (PMID 21122092, 2010). "Body mass index (BMI), fasting plasma glucose (FPG), postprandial plasma glucose (PPG), insulin, HbA1c, and serum endocan levels were significantly higher in the prediabetes group (BMI: p = 0.003; FPG: p < 0.001; PPG: p = 0.019; insulin: p = 0.007; HbA1c: p < 0.001; endocan: p = 0.012)." (PMID 41753283, 2026). "In patients with NCPHPT and prediabetes, mean insulin levels were between 11 μIU/mL and 14 μIU/mL." (PMID 40283231, 2025). "In women with prediabetes, a slightly higher IR or an increased sensitivity of ovaries to the effects of insulin might be responsible for the dynamics between insulin and ovaries." (PMID 41384021, 2025). "Our results showed that high glycemic levels in prediabetes are closely associated with body composition and insulin behavior rather than traditional cardiovascular factors such as blood pressure or cholesterol." (PMID 41394365, 2025). "Thus, the aim of this systematic review of randomized controlled trials (RCTs) is to synthesize evidence on the impact of vitamin D supplementation on insulin sensitivity and glycemic management, specifically in people with prediabetes." (PMID 40004770, 2025). "TCEs, particularly Baduanjin and Qigong, may improve glycemic control, insulin sensitivity, and psychological well-being in individuals with prediabetes, whereas Taiji appears to provide more gradual, long-term benefits." (PMID 41255514, 2025). "Early detection of heightened NE tone could serve as a biomarker and a treatment target, with sympatholytic or β-blocker strategies potentially improving insulin dynamics in prediabetes and new-onset T2D." (PMID 40869170, 2025). "An alternative explanation for the correlation of IR with total testosterone levels being found exclusively in the prediabetes group might be related to the ovarian hypersensitivity to insulin under chronic hyperglycemia." (PMID 41384021, 2025). "Let-7i-5p may regulate systemic insulin sensitivity and serve as a biomarker for prediabetes in women by impairing insulin signaling and glucose homeostasis." (PMID 40162315, 2025). "Exclusion criteria: previous anti-osteoporotic medication, prediabetes, insulin therapy, non-T2D." (PMID 40804864, 2025). "Moreover, HOMA-IR has been shown to increase with both chronological and biological aging, underscoring the role of advancing age in impairing insulin action and thus reducing the likelihood of prediabetes remission." (PMID 40843316, 2025). "The data about residual insulin secretion in different stages of prediabetes are limited." (PMID 40004639, 2025). "In our cohort, IGF-1 levels were higher in women with prediabetes and mediated the effect of insulin on testosterone, suggesting that early dysglycemia may already activate this insulin–IGF-1–androgen axis." (PMID 41384021, 2025).
prediabetes (continued). "Compensatory increases of INS biosynthesis and secretion are features of patients with prediabetes." (PMID 40392602, 2025). "Our findings suggest that hemodynamic and metabolic mechanisms orchestrated by the kidney (likely mediated by insulin dynamics) might be involved in the pathogenesis of early glucose dysregulation leading to prediabetes." (PMID 41163811, 2025). "The mechanisms by which probiotics may regulate blood glucose homeostasis in prediabetes include improving insulin resistance, regulating intestinal permeability, modulating metabolic regulation, and altering the gut microbiota composition." (PMID 39997751, 2025). "Nevertheless, regular exercise in normal-weight individuals with prediabetes confers broad metabolic and cardiovascular benefits, including improved insulin sensitivity, reductions in visceral adiposity, preservation or increases in lean mass, and enhanced cardiorespiratory fitness." (PMID 41377666, 2025). "However, migraineurs with prediabetes had significantly higher fasting insulin, HOMA-IR, and lower QUICKI values compared to prediabetic controls." (PMID 40426647, 2025). "Materials and Methods: A sixteen-weeks randomized controlled trial was conducted to assess the impact of an exercise-based manual program on biochemical markers, such as HbA1c, insulin sensitivity measures, and lipid profiles, in sedentary individuals with prediabetes." (PMID 40005307, 2025). "However, there is limited knowledge regarding the impact of IF on glucose regulation in individuals with prediabetes and an insufficient understanding of its role within the insulin signalling pathway in the long term." (PMID 39861423, 2025). "Consequently, probiotics have been proposed as a potential treatment to enhance metabolic health and prevent type 2 DM or prediabetes by altering intestinal microbiota and controlling insulin signaling." (PMID 40321607, 2025). "Thus, 2 weeks of exercise altered neuronal insulin signaling responses to glucose ingestion and lowered pro‐BNDF among adults with prediabetes, thereby potentially lowering ADRD risk." (PMID 39421964, 2025). "Notably, as compared with women with NGT, those with prediabetes exhibited a 35% lower (P = 0.04) insulin-stimulated myocardial glucose metabolism and women with T2DM a 74% lower value (P = 0.006), respectively." (PMID 38671460, 2024). "The altered glucagon regulation may be caused by insulin resistant alpha cells or by the overall higher protein/food intake in the HFD-fed animals and may over time lead to poor glycemic control and prediabetes as observed in humans." (PMID 38427692, 2024). "Furthermore, Konxhe Kulaj disclosed white adipocyte-derived extracellular vesicles (AdEVs) as stimulants for insulin secretion in early-stage prediabetes." (PMID 39698417, 2024). "Prolonged aerobic exercise may induce multifaceted physiological alterations, improve insulin sensitivity, and enhance energy metabolism, leading to more effective reductions in blood glucose levels among individuals with prediabetes." (PMID 39859972, 2024). "However, two hours after oral glucose administration, the levels of blood glucose, insulin, and C-peptide during both pregnancy and postpartum were significantly elevated in the prediabetes group, compared with the control group." (PMID 39512103, 2024). "Metformin, the most prescribed glucose-lowering medication and taken by 93% of our T2D study participants, has been shown to attenuate the training-enhanced peripheral insulin sensitivity and mitochondrial adaptations, and alters VO2peak improvements in adults with prediabetes." (PMID 39633643, 2024). "Thus, weight loss is an important driver of prediabetes remission and, in PLIS, an improvement in insulin sensitivity was critical for prediabetes resolution." (PMID 38780785, 2024).